TRIM32 (tripartite motif containing 32)
Diseases named in the same sentence as TRIM32 in open-access papers (continued):
Sharing a sentence is not in itself a finding about the gene and the disease.
Insulin resistance (1 paper, 2025). Increased resistance towards insulin, that is, diminished effectiveness of insulin in reducing blood glucose levels. "Altogether, our findings present in vivo evidence supporting TRIM32’s role in the negative regulation of liver insulin receptor signaling in mice with HFD-induced insulin resistance." (PMID 39747658, 2025). "Utilizing a holistic approach encompassing in vitro and in vivo experiments, we identified the E3 ubiquitin ligase TRIM32 as a critical regulator of INSR degradation during the development of HFD-induced insulin-resistance in mice." (PMID 39747658, 2025). "Here, we provide comprehensive evidence linking TRIM family member TRIM32 to insulin resistance and related metabolic disorders." (PMID 39747658, 2025). "In conclusion, our results demonstrate that TRIM32 promotes diet-induced hepatic insulin resistance by targeting the INSR to degradation." (PMID 39747658, 2025). "This study identifies the E3 ubiquitin ligase TRIM32 as a critical factor in the degradation of the INSR, leading to a reduction of membrane-associated INSR protein levels and insulin resistance." (PMID 39747658, 2025). "Here, we tested whether inactivated AMPK (HFD liver) further prompted hypophosphorylation (Ser372) of SREPB-1c and its nuclear translocation, leading to enhanced TRIM32 expression and hepatic insulin resistance." (PMID 39747658, 2025). "Next, we checked whether depletion of TRIM32 in high-fat diet mice liver could rescue from insulin resistance and fatty liver." (PMID 39747658, 2025). "TRIM32 ubiquitylates INSR and facilitates its proteasomal degradation, leading to severe insulin resistance and fat accumulation within the liver of high-fat diet induced obese (DIO) mice." (PMID 39747658, 2025). "To determine the relevance of TRIM32 proteins in insulin resistance and NAFLD, we also examined the expressions of TRIM32 genes using publicly available hepatic transcriptome data for healthy and non-alcoholic fatty liver (NAFLD) patients." (PMID 39747658, 2025).
intestinal inflammation (1 paper, 2025). "Ubiquitination of Trim32 was increased in colonic macrophages from multiple models of intestinal inflammation, including the IBD, GVHD, and HAEC-like intestinal inflammation models." (PMID 40021897, 2025).
keloid (1 paper, 2024). An irregularly shaped, elevated mark on the skin caused by deposits of excessive amounts of collagen during wound healing. "Further research on the inflammatory regulation of scarring by TRIM32 may establish TRIM32 as a potential treatment target for keloids." (PMID 38444850, 2024). "We speculate that TRIM32 is closely involved in the formation of keloids." (PMID 38444850, 2024).
limb-girdle myopathy (1 paper, 2021). "Satellite cells from TRIM32 mutated limb-girdle myopathy patients are characterized by abnormal autophagy activity and an accumulation of TRIM32 substrates." (PMID 33766031, 2021). "As in aging, senescent satellite cells with dysfunctional metabolism are typical of a limb-girdle myopathy caused by mutated TRIM32." (PMID 33766031, 2021).
lymph node metastasis (1 paper, 2025). "Fisher’s exact test showed that TRIM32 expression was significantly correlated with lymph node metastasis and tumor TNM stage (both, p < 0.05)." (PMID 40507857, 2025).
muscle atrophy (1 paper, 2023). The loss of muscle tissue due to inactivity or disease. "The connection of the tripartite motif-containing protein 32 (TRIM32) family with SUMO E3 ligase PIAS4 was among the pioneering studies linking SUMOs with muscle atrophy." (PMID 36831310, 2023).
nemaline myopathy (1 paper, 2023). Nemaline myopathy (NM) encompasses a large spectrum of myopathies characterized by hypotonia, weakness and depressed or absent deep tendon reflexes, with pathologic evidence of nemaline bodies (rods) on muscle biopsy. "Proteolysis in skeletal muscle is closely regulated by E3 ubiquitin ligases such as TRIM32, that was shown to target actin and desmin, and mutations in TRIM32 result in LGMD, nemaline myopathy or MFM." (PMID 37174721, 2023).
neuropathy (1 paper, 2023). A disorder affecting the nervous system that manifests with pain, tingling, numbness, and/or muscle weakness. "Similar to TRIM32-knockout mice, LGMD2H patients with a frameshift (c.1560delC, C521VfsX13) or a deletion mutant of TRIM32 (30-kb intragenic deletion in the TRIM32 gene) showed signs of both myopathy and neuropathy." (PMID 37626915, 2023).
non-small cell lung carcinoma (1 paper, 2021). A group of at least three distinct histological types of lung cancer, including non-small cell squamous cell carcinoma, adenocarcinoma, and large cell carcinoma. "Elevated expression of TRIM32 in non-small cell lung cancer (NSCLC) cell lines induced cisplatin chemoresistance." (PMID 33802079, 2021).
oral squamous cell carcinoma (1 paper, 2025). "The level of TRIM32 is increased in oral squamous cell carcinoma, and promotes disease progression by enhancing the ubiquitination and degradation of FBP2." (PMID 40507857, 2025).
pancreatic cancer (1 paper, 2022). "Additionally, knockdown of TRIM32 diminished mTOR/p70S6K activity in pancreatic cancer cells, indicating a positive feedback loop between TRIM32 and mTOR/p70S6K pathway." (PMID 34921503, 2022). "Moreover, ibr‐7 was able to sensitize pancreatic cancer cells to gemcitabine through the efficient repression of TRIM32, which was positively correlated with the proliferation and invasiveness of pancreatic cancer cells." (PMID 34921503, 2022). "To conclude, this work preliminarily explored the role of TRIM32 in the malignant properties of pancreatic cancer cells and evaluated the possibility of targeting TRIM32 to enhance effectiveness of gemcitabine, thereby providing a novel therapeutic target for pancreatic cancer." (PMID 34921503, 2022).
paraplegia (1 paper, 2017). Complete paralysis of the lower half of the body including both legs, often caused by damage to the spinal cord. "Both TRIM32−/− and TRIM32+/+ littermates became almost complete paraplegia, with extremely poor ankle movement, right after the bilateral dorsal cut hemisection injury." (PMID 28514764, 2017).
primary effusion lymphoma (1 paper, 2024). A large B-cell lymphoma located in the body cavities, characterized by pleural, peritoneal, and pericardial fluid lymphomatous effusions and that is always associated with human herpes virus-8 (HHV-8). "Such inhibition of TRIM32 expression induces cellular apoptosis which, in turn, inhibits the proliferation of KSHV-infected primary effusion lymphoma (PEL) cells." (PMID 39599852, 2024).
renal carcinoma (1 paper, 2020). A carcinoma arising from the epithelium of the renal parenchyma or the renal pelvis. "In renal cancer, TRIM32 promotes cell proliferation and invasion by activating the β-catenin signaling pathway." (PMID 33173411, 2020). "Seven genes (TRIM8, TRIM11, TRIM16, TRIM24, TRIM27, TRIM32, and PML) were expressed in different renal cancer cell lines through the KM expression website." (PMID 33173411, 2020).
Stomach adenocarcinoma (1 paper, 2025). "Subsequent analysis using TIMER database on TCGA data confirmed the elevated expression of TRIM32 in Stomach adenocarcinoma (STAD), and showed a positive association between TRIM32 expression and macrophage abundance, indicating a role of TRIM32 in promoting macrophage enrichment in GC." (PMID 41163195, 2025).
triple-negative breast carcinoma (1 paper, 2024). An invasive breast carcinoma which is negative for expression of estrogen receptor (ER), progesterone receptor (PR), and human epidermal growth factor receptor 2 (HER2). "Nuclear TRIM32 inhibits TC45, leading to upregulated STAT3 and radio resistance in triple-negative breast cancer." (PMID 38727267, 2024). "Similarly, TRIM32 is an E3 ligase and CDK2 substrate that mediates the CDK2 promotion of radio resistance in triple-negative breast cancer." (PMID 38727267, 2024).
vitiligo (1 paper, 2024). Generalized well circumscribed patches of leukoderma that are generally distributed over symmetric body locations and is due to autoimmune destruction of melanocytes. "Regarding ECA25, six significant genomic regions were identified, although genes related to biological processes associated with vitiligo (TXN, LPAR1, SLC46A2, PRPF4, TRIM32, STOM, BRINP1, and DAB2IP) were only found in five of them." (PMID 39199954, 2024).
tumor (27 papers, 2012 to 2026). "TRIM32 originating from tumors was found to be linked to poor prognosis and notably associated with tumor-associated macrophages (TAMs) in." (PMID 41163195, 2025). "The ubiquitous expression of TRIM32 makes it a reasonable candidate to be implicated in muscle function as well as tumor suppression and/or progression." (PMID 33802079, 2021). "Remarkably, TRIM32 is also required for ectopic growth - loss of TRIM32 in a wing disc-associated tumor model reduces glycolytic metabolism and restricts growth." (PMID 32223900, 2020). "These early studies showed that mutations in brat and mei-26, ortholog of TRIM32 in the fly, cause tumor formation in Drosophila." (PMID 27821801, 2016). "In addition, several groups have implicated TRIM32 in tumor formation based on studies initially performed in Drosophila melanogaster." (PMID 27821801, 2016). "Therefore, changing the metabolic balance within cells towards anabolic pathways may be an underlying mechanism for abnormal cell growth in multiple tumor types that overexpress TRIM32." (PMID 33802079, 2021). "PLAAT2 functions as a tumor suppressor in GC by recruiting TRIM32 to facilitate cMyc ubiquitination and impair MEK/ERK-driven oncogenic signaling, highlighting the PLAAT2/TRIM32/cMyc axis as a potential therapeutic target." (PMID 41851102, 2026). "It was demonstrated that the TRIM32/PDE9A-PI3K/AKT pathway enhances tumor suppression by inducing M2-like polarization of macrophages within the TME." (PMID 41163195, 2025). "The results showed that TRIM32 is up-regulated in eight tumor tissues, namely, CHOL, COAD, ESCA, HNSC, LIHC, LUAD, LUSC, and STAD." (PMID 40507857, 2025). "GC mouse model was utilized along with flow cytometry analysis, transwell assays, and immunohistochemistry to investigate the impact of TRIM32 on tumor progression and macrophage." (PMID 41163195, 2025). "The specific effects of down-regulation of TRIM32 expression on the proliferation, migration, and apoptosis of CRC cells were investigated, and the anti-tumor effect and molecular mechanism of TRIM32 on CRC were examined by Western blotting." (PMID 40507857, 2025). "Our research confirms the significance of PI3K/AKT pathway in the induction of M2 macrophages by TRIM32, enhancing our comprehension of its impact on tumor immunity." (PMID 41163195, 2025). "Immunofluorescence analysis revealed higher levels of TRIM32 protein in tumor tissues versus normal tissues." (PMID 41163195, 2025). "TRIM32 is up-regulated in benign and malignant tumors, and plays a carcinogenic role in tumor growth." (PMID 40507857, 2025). "As a E3 ubiquitin ligase, TRIM32 plays important roles in several cellular process, including differentiation, tumor suppression, regeneration, microRNA process, muscle physiology, and antiviral innate immunity." (PMID 38895352, 2024). "In contrast, as a tumor suppressor, TRIM32 contributes to the death of different types of cancer cells, such as breast cancer, pancreatic cancer, lung cancer, gastric cancer, and colorectal cancer cells." (PMID 37626915, 2023). "As tumor biology continues to advance, the relationship between TRIM32 and tumor progression is receiving increasing attention." (PMID 35756612, 2022). "Recently, a variety of studies have proved that TRIM32 is closely related to glucose metabolism both in normal and tumor tissues by interaction with two enzymes involved in glycolysis." (PMID 35756612, 2022). "Human tripartite motif family of proteins 32 (TRIM32) is a ubiquitous multifunctional protein that has demonstrated roles in differentiation, muscle physiology and regeneration, and tumor suppression." (PMID 33802079, 2021). "TRIM32 also functions as a tumor suppressor, but paradoxically is overexpressed in certain types of cancer." (PMID 33802079, 2021). "Another tumor suppressor function of TRIM32 was defined in its ability to facilitate the proteasomal degradation of MYCN in neuroblastoma cells." (PMID 33802079, 2021).
tumor (continued). "Amplification of the MYCN oncogene has been observed in retinoblastoma, glioblastoma, and medulloblastoma tumors, and raises the possibility that TRIM32 plays a broader role in tumor suppression than previously thought." (PMID 33802079, 2021). "TRIM32 mRNA and/or protein is upregulated in benign and malignant tumors, suggesting a potential role for this E3 ligase in tumor progression." (PMID 33802079, 2021). "Drosophila TRIM32 promotes cell growth in normal and tumor tissues that exhibit elevated glycolytic flux." (PMID 33802079, 2021). "TRIM32 is reported to act both as an oncogene and as tumor suppressor, depending on the specific organ and cellular context." (PMID 33999923, 2021). "Overall, our results reveal a novel role for TRIM32 for controlling glycolysis in the context of both normal development and tumor growth." (PMID 32223900, 2020). "Knockdown TRIM32 expression remarkably suppressed the proliferation, migration, and invasion of GC cells in vitro and tumour growth in vivo, whereas overexpression of TRIM32 yielded the opposite results." (PMID 30079558, 2018). "To further explore the biological significance of β‐catenin in the TRIM32‐mediated tumour promotion, we studied the effect of the β‐catenin inhibitor iCRT3 on cell viability and migratory and invasive capabilities of TRIM32‐overexpressing MKN28 cells." (PMID 30079558, 2018). "Some TRIMs, such as TRIM13, TRIM8, and TRIM32, function as tumour suppressor proteins through regulation of transcription and apoptosis." (PMID 23404198, 2013). "This further verified the regulatory role of TRIM32 in the process of CRC tumor growth." (PMID 40507857, 2025). "Tumor volume and weight measurements were taken to assess whether the reduced tumor growth observed with TRIM32 knockdown was due to diminished macrophage recruitment." (PMID 41163195, 2025). "This research provides insight into the role of TRIM32 in modulating tumor immunity and suggests that TRIM32 could be a promising target to overcoming resistance to anti-PD-1 therapy in GC." (PMID 41163195, 2025). "TRIM32 functions as both an oncogenic protein and a tumor suppressor." (PMID 37626915, 2023). "Similarly to other members of this family, TRIM32 is involved in cancer development and its pro-oncogenic action has been described in different tumor contexts, including SCCs." (PMID 32560247, 2020). "Importantly, TRIM32 protein levels are upregulated in multiple tumor types, suggesting that TRIM32 is a key player in growth regulation." (PMID 32223900, 2020). "All these findings suggest that TRIM32 is involved in tumor formation and development." (PMID 31820796, 2019). "Furthermore, N-myc downstream regulated gene 2 (NDRG2), a new tumor suppressor gene that has recently been reported to suppress the growth and aggressiveness of NB cells, is identified as a novel target for TRIM32." (PMID 31820796, 2019). "All these findings suggest TRIM32 to be a tumor suppressant gene and further studies could demonstrate the identical function in different tumor models as well." (PMID 29479529, 2018). "On the other hand, lentiviral expression of TRIM32 resulted in accelerated xenograft tumour growth." (PMID 30079558, 2018). "TRIM32 promotes GC cell proliferation, migration, invasion, and xenograft tumour growth." (PMID 30079558, 2018).
tumor (continued). "Thus, TRIM32 in tumor cells promotes M2-like TAM polarization and T cell dysfunction." (PMID 41163195, 2025). "The inhibitory effect of TRIM32 on CRC in vivo was evaluated by measuring tumor volume and weight, Hematoxylin and eosin (H&E) staining, and Ki67 IHC staining in heterotopic tumor-forming mice with CRC." (PMID 40507857, 2025). "In order to further investigate the role of TRIM32 in tumor growth, experiments were carried out with a HCT116 cell murine subcutaneous xenograft tumor model." (PMID 40507857, 2025). "Age, distant metastasis, tumor TNM stage, and TRIM32 expression are independent prognostic factors for OS." (PMID 40507857, 2025). "An in vivo model was used to verify the inhibitory effect of TRIM32 on CRC using tumor volume and weight measurement, Hematoxylin and eosin (H&E) staining, and Ki67 immunohistochemistry (IHC) staining of tumor tissue." (PMID 40507857, 2025). "Thus, we hypothesized that TRIM32 could be a general regulator of highly glycolytic tumor cells." (PMID 32223900, 2020). "Like TRIM24/TIF1α and TRIM32, TRIM16 has been shown to suppress tumour progression through regulatory pathways involved in growth inhibition, migration, differentiation and apoptosis." (PMID 23404198, 2013). "Since in the absence of TRIM32, Pax7+ muscle stem cells fail to differentiate, one may hypothesise that this lack of differentiation could lead to tumour formation." (PMID 22299041, 2012). "However, we never observed tumours in the muscle or any other tissue in TRIM32 knock-out mice." (PMID 22299041, 2012).